WDR93 (WD repeat domain 93)
Synonyms: FAP297; C1d-87; CFAP297
Tractability: No criterion of Open Targets' tractability assessment is met for any kind of drug.
Gene: Protein-coding gene on chromosome 15 (89,690,811 to 89,743,639, forward strand). Ensembl gene ENSG00000140527.
Subcellular location (Human Protein Atlas): Actin filaments
Gene Ontology:
Biological process: electron transport chain
Genetic constraint (gnomAD): Loss-of-function variants: 66 observed, 76.81 expected, observed/expected ratio (o/e) 0.86, 90% interval 0.7 to 1.05. The upper end of that interval is the gene's LOEUF score, 1.05, which puts it in group 4 of 6, group 1 being the genes least tolerant of losing a copy. Missense variants: 664 observed, 786.29 expected, observed/expected ratio (o/e) 0.84, 90% interval 0.79 to 0.9. Synonymous variants: 262 observed, 293.11 expected, observed/expected ratio (o/e) 0.89, 90% interval 0.81 to 0.99.
Homologues: Orthologues: chimpanzee WDR93 (99% identical), macaque WDR93 (94% identical), dog WDR93 (77% identical), pig WDR93 (73% identical), rat Wdr93 (65% identical), mouse Wdr93 (65% identical), zebrafish wdr93 (27% identical), tropical clawed frog wdr93 (20% identical). Paralogues in human: NDUFS4 (5% identical).
Diseases named in the same sentence as WDR93 in open-access papers:
WDR93 is named in the same sentence as 3 diseases in open-access papers, as found by Europe PMC text mining. Sharing a sentence is not in itself a finding about the gene and the disease. The quoted sentences say what the papers report.
influenza infection (1 paper, 2023). "Evidence from transcriptome studies of the host response to influenza infection supports the role of WDR93 in countering respiratory pathogens." (PMID 37621660, 2023). "Nonetheless, the WDR93 and CFAP46 gene disruption patterns suggest their loss could have functional significance for influenza infection." (PMID 37621660, 2023).
virus infection (1 paper, 2023). "A transcriptomic study of the differential host response to high or low pathogenic H5N1 avian influenza virus in ducks has identified WDR93 (also known as CFAP297) to be down-regulated in high and up-regulated in low pathogenic virus infection." (PMID 37621660, 2023).
WDR93 also shares sentences with these, for which no sentence is quoted: psychiatric disorder (1 paper).